NMB (neuromedin B)
Description:
Stimulates smooth muscle contraction (By similarity). Induces sighing by acting directly on the pre-Botzinger complex, a cluster of several thousand neurons in the ventrolateral medulla responsible for inspiration during respiratory activity (By similarity). Contributes to the induction of sneezing following exposure to chemical irritants or allergens which causes release of NMB by nasal sensory neurons and activation of NMBR-expressing neurons in the sneeze-evoking region of the brainstem (By similarity). These in turn activate neurons of the caudal ventral respiratory group, giving rise to the sneezing response (By similarity). Contributes to induction of acute itch, possibly through activation of the NMBR receptor on dorsal root ganglion neurons (By similarity). Increases expression of NMBR and steroidogenic mediators STAR, CYP11A1 and HSD3B1 in Leydig cells, induces secretion of testosterone by Leydig cells and also promotes Leydig cell proliferation (By similarity). Plays a role in the innate immune response to influenza A virus infection by enhancing interferon alpha expression and reducing expression of IL6. Plays a role in CSF1-induced proliferation of osteoclast precursors by contributing to the positive regulation of the expression of the CSF1 receptor CSF1R (By similarity).
Synonyms: MGC2277; MGC3936; MGC17211
Tractability: Antibody: its Gene Ontology location is reachable by antibodies, with high confidence; UniProt places it where antibodies can reach, with medium confidence; UniProt predicts a signal peptide or a membrane-spanning region; the Human Protein Atlas places it where antibodies can reach.
Gene: Protein-coding gene on chromosome 15 (84,655,129 to 84,658,563, reverse strand). Ensembl gene ENSG00000197696.
Subcellular location: Secreted; Cell projection, neuron projection
Subcellular location (Human Protein Atlas): Golgi apparatus; Cytosol; Focal adhesion sites; Plasma membrane; Predicted to be secreted
Pathways (Reactome):
Signal Transduction: G alpha (q) signalling events; Peptide ligand-binding receptors
Gene Ontology:
Molecular function: protein binding; hormone activity; neuromedin B receptor binding; neuropeptide hormone activity
Biological process: antiviral innate immune response; cell-cell signaling; Leydig cell proliferation; negative regulation of interleukin-6 production; neuropeptide signaling pathway; positive regulation of hormone secretion; positive regulation of interferon-alpha production; positive regulation of osteoclast proliferation; positive regulation of respiratory gaseous exchange; positive regulation of testosterone secretion; sensory perception of itch; signal transduction; sneeze reflex; arachidonate secretion; negative regulation of hormone secretion; positive regulation of cell population proliferation; positive regulation of cytosolic calcium ion concentration
Cellular component: extracellular region; neuron projection
Genetic constraint (gnomAD): Loss-of-function variants: 13 observed, 13.43 expected, observed/expected ratio (o/e) 0.97, 90% interval 0.63 to 1.53. The upper end of that interval is the gene's LOEUF score, 1.53, which puts it in group 6 of 6, group 1 being the genes least tolerant of losing a copy. Missense variants: 174 observed, 140.76 expected, observed/expected ratio (o/e) 1.24, 90% interval 1.09 to 1.4. Synonymous variants: 76 observed, 62.38 expected, observed/expected ratio (o/e) 1.22, 90% interval 1.01 to 1.47.
Homologues: Orthologues: chimpanzee NMB (91% identical), macaque NMB (80% identical), pig NMB (71% identical), dog NMB (69% identical), mouse Nmb (67% identical), guinea pig NMB (65% identical), rat Nmb (65% identical), zebrafish nmba (31% identical), zebrafish nmbb (28% identical). Paralogues in human: GRP (27% identical).
Diseases named in the same sentence as NMB in open-access papers:
NMB is named in the same sentence as 64 diseases in open-access papers, as found by Europe PMC text mining. Sharing a sentence is not in itself a finding about the gene and the disease. The quoted sentences say what the papers report.
Obesity (8 papers, 2011 to 2023). Accumulation of substantial excess body fat. "Neuromedin B is a peptide that acts on hypothalamic neurons to promote satiety, and a missense mutation is linked to hyperphagia and obesity in genetic studies." (PMID 37143734, 2023). "Several GWAS studies on non-obese and obese patients suggested that polymorphisms in NMB predispose to obesity by affecting appetite control and feeding preference." (PMID 35672347, 2022). "Another study reported the influence of maternal education on the effect of a variant of the neuromedin B gene on obesity." (PMID 28690685, 2017). "Rs2292462 lies within the obesity-implicated neuromedin B gene." (PMID 23879873, 2013). "Interestingly, in adolescence, the association between the polymorphism on the NMB gene and obesity was exacerbated in families of lower socio-economic status." (PMID 24298233, 2013). "Polymorphism in NMB is associated with obesity, but this gene may link with insulin resistance." (PMID 30678306, 2019). "Importantly, human NMB mutant carriers were reported to develop obesity due to appetite disinhibition and high calorie meal preference." (PMID 35672347, 2022). "Studies in humans and animals have shown that administration of CCK, PYY, GLP-1, and NMB could decrease food intake but administration of ghrelin and NPY leads to obesity." (PMID 21390334, 2011).
breast carcinoma (4 papers, 2015 to 2025). "In addition to its physiological functions, the NMB-NMBR axis participates in a wide variety of pathological activities, especially in malignancies such as lung cancer, colorectal cancer, glioma, breast cancer, and cervical cancer." (PMID 39214988, 2024). "Although possible anti-apoptotic effects of NMB on VECs and vascular myocytes have not been reported, PD168368, an inhibitor of the NMB receptor, suppressed the growth of breast cancer cells by inducing cell cycle arrest and apoptosis, suggesting that NMB may have anti-apoptotic activity." (PMID 26207818, 2015).
itch (4 papers, 2017 to 2025). "Studies have highlighted the involvement of NMB in AD-associated pruritus, focusing on its expression levels and interactions with other neuropeptides." (PMID 41346997, 2025). "Beyond its role in pruritus, NMB may regulate type 2 immune responses by modulating group 2 innate lymphoid cells (ILC2s), key mediators of neuro-epithelial-immune crosstalk." (PMID 41346997, 2025). "We hypothesize that such itch induction is due to the NMB directly binding to the NMBR on sensory neurons." (PMID 30734045, 2019). "Chemically evoked itch signals originate from DRG neurons expressing Mrgprs, Nppb NMB." (PMID 41248150, 2025). "Thus, we propose that NMB and GRP may transmit discrete itch information and NMBR neurons are an integral part of neural circuits for itch in the spinal cord." (PMID 29133874, 2017).
neuroblastoma (4 papers, 2014 to 2024). Neuroblastoma (NB) is the most common solid, extracranial childhood tumor. "Some studies also support a role for NMB/NMBR in affecting neuroblastoma cell line survival, proliferation, and viability." (PMID 34539578, 2021). "Furthermore, NMB significantly stimulated the survival of SH-SY5Y cells derived from human neuroblastoma tissue with characteristics similar to neurons." (PMID 26207818, 2015). "It is worth noting that the NMB-NMBR axis can mediate the release of chemokines, such as IL-4 in the intestine, IL-8 in neuroblastoma, and VEGF in tumor." (PMID 39214988, 2024). "In one study similar to NGF, NMB administration prolonged the survival of the neuroblastoma cell line SH-5Y, although it did not promote neuron-like differentiation of these cells, whereas NGF did." (PMID 34539578, 2021).
schizophrenia (4 papers, 2020 to 2022). A major psychotic disorder characterized by abnormalities in the perception or expression of reality. "Upregulation of Neuromedin B (NMB), for which expression was not significantly cis-heritable in the brain, was associated with schizophrenia and BIP risk." (PMID 32398653, 2020).
allergic dermatitis (2 papers, 2019 to 2025). "A number of pharmacological agents acting on NMB-related pathways have been reported to exert beneficial effects in the context of atopic dermatitis." (PMID 41346997, 2025). "The potential of neuromedin B as a pruritogen and pro-inflammatory peptide in the skin was tested in vivo in an acute model in mice and monkeys as well as an allergic dermatitis model in mice." (PMID 30734045, 2019). "Quantitative analysis revealed that the expression of NMB, IL2RA, IL1RL1, and PRKCQ was markedly elevated in individuals with atopic dermatitis relative to healthy controls (p < 0.05 or p < 0.01), indicating their possible involvement in disease development." (PMID 41346997, 2025).
cervical cancer (2 papers, 2024). A primary or metastatic malignant neoplasm involving the cervix. "The analysis of high-frequency ultrasound (HFUS), anatomical analysis, and HE staining were then performed, and the migration distance of cervical cancer cells along sciatic nerve decreased by NMB deficiency were observed." (PMID 39214988, 2024). "Furthermore, the reprograming and activation of Schwann cells was decreased by the co-culture with NMB-deficient HeLa or ME180 cells, confirming that cervical cancer-derived NMB promotes the reprogramming of Schwann cells." (PMID 39214988, 2024). "However, the molecular mechanism underlying the high transcriptional expression of NMB in cervical cancer PNI remains unknown and requires further study." (PMID 39214988, 2024). "Our data demonstrate that cervical cancer-produced NMB initiates the reprograming of Schwann cells, which then direct axon regeneration, thus causing PNI onset." (PMID 39214988, 2024). "The effect of NMB on axon regeneration was analyzed in the DRG-cervical cancer co-culture model, and the regenerated neurites were significantly decreased by the deficiency of NMB or the inhibition of NMBR." (PMID 39214988, 2024). "To determine the potential role of NMB in PNI of cervical cancer, we examined the production of NMB in cervical cancer tissues, especially in those with PNI." (PMID 39214988, 2024). "Moreover, the innervation of cervical cancer was also analyzed by PGP9.5 staining, and it was also decreased by NMB deficiency, which is rescued by NMB administration." (PMID 39214988, 2024). "Thus, tumor-derived NMB acts as a signal that initiates PNI by reprogramming Schwann cells via NMBR in cervical cancer." (PMID 39214988, 2024). "The function and mechanism of cervical cancer-produced NMB in the initiation and progression of PNI were then determined both in vitro and in vivo, as well as in cervical cancer patients, suggesting its potential in the prediction of PNI and the targeted therapy." (PMID 39214988, 2024). "The combined examination of serum NMB and CCL2 may serve as diagnostic indicators to predict PNI before operation in cervical cancer patients, and help to identify whether these patients could choose NSRH surgery." (PMID 39214988, 2024). "However, the role of NMB in cervical cancers is limited to tumor proliferation via ERK1/2 and NF-κB pathways and TNF-α upregulation." (PMID 39214988, 2024). "The expression of these genes in cervical cancer cells co-cultured with RSC96 cells or DRG were analyzed by qRT-PCR, and we found that NMB mRNA and protein was the most increased in the co-culture system, suggesting that cervical cancer-derived neuropeptide NMB may initiate PNI in cervical cancer." (PMID 39214988, 2024). "In this study, we also found that NMB induced the secretion of CCL2 by Schwann cells via a NMBR-dependent induction of a Ca2+ influx, which determines this NMB-NMBR-CCL2 axis in the activation of Schwann cells and the initiation of PNI in cervical cancer." (PMID 39214988, 2024). "Moreover, combined examination of NMB and CCL2 showed the discrimination of PNI with the AUC value of 0.914 (95% CI 0.828-1.000) in cervical cancer as compared to that of NMB or CCL2 alone, which may be clinical effective for the preoperative evaluation of PNI." (PMID 39214988, 2024). "CCL2 expression in RSC96 cells was markedly induced by its co-culture with cervical cancer cells, and its expression could be induced by the administration of recombinant NMB, while this induction was abolished by the inhibition using PD168368 or deficiency of NMB." (PMID 39214988, 2024). "The serum level of CCL2 in cervical cancer patients was also examined, and it was significantly higher in patients with PNI, positively correlated with serum NMB, and significantly predicted PNI." (PMID 39214988, 2024).
cervical cancer (continued). "When the binding between NMB and NMBR was blocked, the damaged limb function three days post cervical cancer inoculation was reduced, showed by the alleviated sciatic nerve index and sciatic nerve score." (PMID 39214988, 2024). "Clinically, combined examination of serum NMB and CCL2 levels was suggested to effectively predict PNI in cervical cancer patients." (PMID 39214988, 2024). "Since NMB is a secretory protein, its serum level was also significantly increased in cervical cancer patients with PNI compared to those without PNI, with the activity in diagnosing PNI at an AUC value of 0.864 (0.741–0.987, 95% CI)." (PMID 39214988, 2024). "We previously found that PNI did not occur in cervical cancer SiHa and CaSki cells, and NMB was determined to be not expressed by these two cell lines." (PMID 39214988, 2024). "Moreover, research by Ting Huang demonstrated that neuromedin B (NMB), derived from cervical cancer cells, triggers the reprogramming of SCs by binding to its membrane receptor NMBR, which in turn promotes axonal regeneration and induces PNI." (PMID 39061654, 2024). "The elevated serum NMB and CCL2 levels may be useful for the decision-making to nerve sparing during hysterectomy surgery of cervical cancer patients." (PMID 39214988, 2024). "Thus, NMB-activated Schwann cells trigger axon regeneration, which may promote PNI of cervical cancer." (PMID 39214988, 2024). "Furthermore, the NMB protein level was significantly higher in cervical cancer tissues with PNI than those without PNI." (PMID 39214988, 2024). "Furthermore, using both serum CCL2 and NMB, it presented a better discrimination in predicting PNI with an AUC of 0.919 (95% CI 0.838-1.000), suggesting that the combined examination of NMB and CCL2 may be a useful approach to diagnose PNI in cervical cancer patients." (PMID 39214988, 2024).
colon carcinoma (2 papers, 2020 to 2022). "A lower outcome is obtained for 68Ga-DOTA-NMB and 68Ga-DOTA-NMB-AuNP on colon cancer cell line HT-29, for which the uptake profile follows an up and down trend, an indicator of unstable binding to neuromedin B receptors (NMB, BBRS2, BBRS3)." (PMID 32722221, 2020). "Only eight genes (UCN, TRIM, RBCK1, TPM2, CD36, NMB, PPARGC1A, and LGALS4) significantly affected the OS in patients with colon cancer (P < 0.05)." (PMID 35572595, 2022). "In our study, based on the colon cancer immune gene datasets, we used WGCNA to identify 21 immune-related hub genes affecting patients’ OS and constructed IRGPI based on 8 independent OS prognostic factors (UCN, TRIM58, RBCK1, TPM2, CD36, NMB, PPARGC1A, and LGALS4)." (PMID 35572595, 2022).
colorectal cancer (2 papers, 2024 to 2025). A primary or metastatic malignant neoplasm that affects the colon or rectum. "NMB exhibits significant overexpression in colorectal cancer, demonstrating promising potential as a dual-functional biomarker for both diagnostic identification and prognostic evaluation in CRC cases." (PMID 40486508, 2025). "In conclusion, our integrated analysis of public databases and clinical CRC cases has identified NMB as a significant prognostic biomarker for colorectal cancer." (PMID 40486508, 2025). "In conclusion, our comprehensive database analysis and experimental findings collectively establish NMB as a novel biomarker for colorectal cancer (CRC)." (PMID 40486508, 2025).
glioma (2 papers, 2024). A benign or malignant brain and spinal cord tumor that arises from glial cells (astrocytes, oligodendrocytes, ependymal cells). "Finally, neuromedin B increases the expression of the c-fos gene, favors the release of arachidonic acid, and promotes growth in C6 glioma cells." (PMID 39063232, 2024). "High expression of neuromedin B is associated with higher survival of patients with glioma, and the survival rate of patients with gliomas is poorer when the expression of GH-RH is lacking." (PMID 39063232, 2024). "The following peptides, through their respective receptors, promote glioma progression (proliferation, migration, invasion, and angiogenesis): AMD, angiotensin II, GRP, bradykinin, CCK, endothelin, neuromedin B, neurotensin, and substance P." (PMID 39063232, 2024).
non-small cell lung carcinoma (2 papers, 2017 to 2020). A group of at least three distinct histological types of lung cancer, including non-small cell squamous cell carcinoma, adenocarcinoma, and large cell carcinoma. "NMB is present in both SCLC and non-small cell lung cancer (NSCLC) cells, and after secretion it binds to cell surface BB1R stimulating proliferation." (PMID 28785244, 2017). "The bombesin-like peptide neuromedin B (NMB) is present in the central nervous system and gastrointestinal tract of mammals, stimulates smooth muscle contraction and is an autocrine growth factor in non-small cell lung cancer." (PMID 32722221, 2020).
viral infection (2 papers, 2019 to 2024). "The expression level of NMB was slightly increased, whereas the expression of NMBR was clearly increased, in 293T cells in response to virus infection." (PMID 31601264, 2019). "We identified RTN neurons by the mRNA expression of the neuropeptide NMB and observed a reduced number in both total Nmb and Nmb+/PHOX2B+ neurons in PHOX2B shRNA-treated rats compared to naive and NT-shRNA rats two weeks after viral infection." (PMID 38727716, 2024). "However, the expression profiles of NMB and NMBR during IAV infection and the activity of NMB/NMBR in hosts during virus infection remain unclear." (PMID 31601264, 2019).
age-related macular degeneration (1 paper, 2023). Age-related loss of vision in the central portion of the retina (macula), secondary to retinal degeneration. "VPS54 is reported to be associated with Retinitis pigmentosa; IQGAP1 is reported to regulate choroidal vascularization in Age-Related Macular Degeneration; NMB is involved in RPE homeostasis regulation; MC5R is reported to regulate lacrimal gland function." (PMID 37359372, 2023).
anxiety disorder (1 paper, 2024). A category of psychiatric disorders which are characterized by anxious feelings or fear often accompanied by physical symptoms associated with anxiety. "Notably, among the four DE GPCRs identified in both models, Smo has established associations with depressive or anxiety disorders, and our previous study has revealed the role of neuromedin B (NMB) receptor (NmbR) in developing depressive-like symptoms in the animal model." (PMID 38670310, 2024).
dementia (1 paper, 2021). Loss of intellectual abilities interfering with an individual's social and occupational functions. "To date, few studies exploring the association between neuromedin B and dementia exist in literature." (PMID 34408722, 2021).
eating disorder (1 paper, 2022). A broad group of psychological disorders with abnormal eating behaviors leading to physiological effects from overeating or insufficient food intake. "However, it is possible that certain eating disorders in humans that are associated with psychological and social problems but are difficult to model in mice, such as binge eating, can drive increased weight gain in carriers of NMB polymorphisms." (PMID 35672347, 2022).